KRAS (KRas proto-oncogene, GTPase)
Diseases named in the same sentence as KRAS in open-access papers (continued):
Sharing a sentence is not in itself a finding about the gene and the disease.
cancer (continued). "Furthermore, since cancer patients with KRAS mutations do not benefit from anti-epidermal growth factor receptor (EGFR) monoclonal antibodies, KRAS mutation testing can guide anti-EGFR therapy selection." (PMID 33467412, 2021). "It was found that BRAF V600E, RET/PTC1 and TERT mutations were associated with aggressive characteristics, whereas BRAF K601E, HRAS, NRAS, KRAS, PAX8-PPARy mutations and tumors with no mutations are significantly less likely to be associated with high risk cancers." (PMID 33910629, 2021). "KRAS dependency varies across cell models harbouring mutant KRAS, meaning that some KRAS mutant cancers might not be driven by KRAS signaling." (PMID 34064232, 2021). "In KRAS-driven cancers, Atg7 depletion did not affect the antiproliferative effect of CQ, suggesting that the antitumor effect of CQ might be independent of autophagy." (PMID 34844627, 2021). "MTT assay results of scFv-mHALT-1 and mHALT-1-scFv recombinants showed that these immunotoxins could elicit cytotoxic effects on KRAS-positive cancer cells without affecting normal fibroblast cells." (PMID 33959410, 2021). "KRAS E76D has not been reported in other types of cancer, and further study was needed whether if it has a role of an activating mutation." (PMID 34525976, 2021). "In addition, we subdivided the cancer samples into two groups: (i) tumors that had known clinically relevant mutations in EGFR signaling genes: EGFR, KRAS, NRAS, and BRAF, and (ii) “wild type” tumors that did not have these mutations." (PMID 33748471, 2021). "Thus, this demonstrates the importance of being able to target the KRAS-isoform specifically, but irrespective of its mutant status, for utility as a potential cancer therapy." (PMID 34193876, 2021). "Given the evidence from ongoing clinical trials that a substantial proportion of KRAS G12C mutant cancer patients do not benefit from KRAS inhibition therapy, we explored whether the FAK–YAP axis may explain the resistance to KRAS G12C inhibition." (PMID 34151545, 2021). "Since then, mutant KRAS has been identified as an important oncogenic driver for various types of solid malignancies (e.g., NSCLC, pancreatic and colorectal cancer) that promotes cancer initiation, maintenance and progression in genetically engineered mouse models (GEMMs)." (PMID 33809660, 2021). "Interestingly, these metabolic alterations elicited by CDE-metabolite were independent of oncogenic KRAS in pancreatic cancer, suggesting CAFs’ ability to reprogram and support cancer cell metabolism independent of oncogene activation." (PMID 34888248, 2021). "If this is true, identification of signaling molecules functioning in cooperation with KRAS may allow for the development of a new strategy for suppressing cancer without the use of KRAS inhibitors." (PMID 33982211, 2021). "The abnormal activation of KRAS occurs in pancreatic ductal adenocarcinoma, nonsmall cell lung cancer NSCLC, colorectal cancer, and other tumors which can promote ROS generation and the metabolic reprogramming of cancer cells by regulating mitochondria function." (PMID 34484567, 2021). "Moreover, several findings support an intimate relationship between KRAS and MYC, which seem to cooperate and maybe even act interdependently in cancer cell metabolic reprogramming." (PMID 34503295, 2021). "However, some KRAS mutant cancer cells become independent of KRAS for their survival by activating diverse bypass networks that maintain essential survival signaling originally governed by mutant KRAS." (PMID 34680229, 2021).
cancer (continued). "Targeting PI3K and/or mTOR effector proteins downstream of KRas, has been an alternative route apart from targeting the MAPK-ERK protein pathway that is synergistic with combined MAPK/ERK inhibition and similar to ERK inhibition and has overcome resistant cancer cell lines." (PMID 34680208, 2021). "However, half of the cases that developed tumors evolved to metastasis, showing cancer progression which was independent of KRAS expression." (PMID 34781949, 2021). "It is known that KRas mutant cancers are not dependent on EGFR signaling." (PMID 34853306, 2021). "In addition, our work proves Drosophila as a powerful model for the rational design of targeted therapies for genetic subsets of RAS-driven cancers, and suggests that the LKB1 subset of KRAS-driven cancers may benefit from targeting of the CAMKK/AMPK circuit." (PMID 33514834, 2021). "Although there has not yet been successful clinical application of agents targeting KRAS activation, recent studies have suggested drugs that target molecules downstream of KRAS signaling, such as MEK, as novel therapeutic targets for the treatment of KRAS‐activated carcinomas." (PMID 33783985, 2021). "Additionally, more than half of the LGD SNADETs (60%; 3/5) already had KRAS or BRAF alterations, which might result in progression to HGD or carcinoma." (PMID 34584977, 2021). "Here, we found that the anticancer effect of vitamin C can be potentiated in different in vitro and in vivo mouse models by STS/FMD treatment selectively in KRAS-mutant cancers, through a mechanism that is independent of glucose, but that involves differential regulation of HO-1." (PMID 32393788, 2020). "However, despite its well-recognized importance in cancer malignancy, there are no approved therapies for KRAS mutant cancer." (PMID 32629823, 2020). "In comparison with parent cells with KRAS mutation alone, cells with concomitant EGFR mutation exhibited higher sensitivity to EGFR-tyrosine kinase inhibitors (TKIs) but not to conventional anti-cancer drugs." (PMID 32130260, 2020). "Recent studies have found that mutant KRAS allelic imbalance is common in human cancers, highlighting that the increased mutant KRAS dosage, rather than a single allelic mutant KRAS alone, plays a more important role in the accentuated KRAS signaling, tumorigenesis, and metastasis." (PMID 32764295, 2020). "However, for other KRAS mutations, small molecule drugs still remain elusive, with no effective targeted therapy at present for patients with KRAS-mutant cancer." (PMID 32903495, 2020). "Interestingly, p.G12D, which is the most frequent KRAS mutant in cancer, appears to be most similar in its dynamics to wtKRAS, not at all altering the interaction with PI3Kα." (PMID 32708575, 2020). "To examine whether the predicted CMap drugs could exhibit KRAS-dependent cytotoxicity in PDAC cells, we employed the CellMinerCDB database that is a web-based tool enabling to explore and analyze pharmacological and genomic data of human cancer cell lines." (PMID 32947833, 2020). "Among these downstream effectors, there are other molecules targeted by miR-193a-3p or miR-193a-5p: KRAS, a target of miR-193a-3p, and PIK3R3 and mTOR, targets of miR-193a-5p, which are all proteins stimulating proliferation, cell cycle progression, and cell survival in cancer cells." (PMID 32867069, 2020). "We observed this behavior in HeLa cells, three different KRAS mutant cancer cell lines, and mouse embryonic fibroblast (MEF) cells that only express one isoform of human RAS at a time In all cells tested, KRAS4b molecules show three different diffusion components." (PMID 31958057, 2020).
cancer (continued). "In addition, in-vitro and in-vivo reverse genetics experiments in pancreatic ductal adenocarinoma (PDAC) revealed that cancer cells rely on a non-canonical pathway of glutamine metabolism, which is strictly regulated by KRAS." (PMID 32932943, 2020). "In turn, both mutant and nonmutant KRAS favor the Warburg phenotype in cancer cells." (PMID 31600993, 2019). "Interestingly, many pathways such as KRAS signaling, inflammatory response and spermatogenesis had non-zero kernel-based importance scores across many cancer types." (PMID 31416413, 2019). "Interestingly, CDE metabolic reprogramming was shown to be independent of oncogenic KRAS in pancreatic cancer, thereby demonstrating CAFs’ ability to reprogram and support cancer cell metabolism independent of oncogene activation." (PMID 31058816, 2019). "Therefore, numerous efforts made by industry and academic laboratories have failed to design a drug to inhibit KRAS activity in cancer cells by directly targeting KRAS." (PMID 30971271, 2019). "Interestingly, STAT3 activation seems to be a general mechanism of acquired resistance since it was also observed in cancer cells driven by diverse kinases, including EGFR, HER2, ALK, and MET, as well as mutant KRAS following treatment with specific inhibitors." (PMID 30622697, 2019). "Together, these studies provided compelling evidence that C-Raf, but not B-Raf or A-Raf, may mediate the oncogenic signaling in KRAS-driven cancer." (PMID 31612108, 2019). "Even though a putative GAP inhibitory mechanism could explain the inhibition of KRASWT/K27 interaction by K13/K19, it is not the mechanism that prevails in either mutant KRAS or KRASWT cancer cells." (PMID 31197133, 2019). "Currently, there are no effective targeted therapies for patients with KRAS mutant cancers." (PMID 30971271, 2019). "AZ628 and BP-1-102 combination significantly inhibited the growth of KRAS-mutant cancer cells and tumors, whereas single agent only had slight inhibition ability, which is consistent to the report of previous study that RAF inhibitors show little efficacy in KRAS mutant cancers." (PMID 31484165, 2019). "The absence of the clinically relevant mutations in KRAS and BRAF in MBC02 suggests that cancer pathogenesis may have been driven by some other mechanism." (PMID 30828563, 2019). "However, this phenomenon was only observed in KRAS and BRAF mutant cancer cells." (PMID 31096937, 2019). "Therefore, our data also suggest that inhibition of both WT and mutant KRAS do not affect the RAS downstream signalling pathways of RASWT cancer cells." (PMID 31197133, 2019). "Atypical endometrial hyperplasia/EIN and EC shares several molecular alterations with each other, including microsatellite instability, PAX2 inactivation, mutation of PTEN, KRAS, and CTNNB1 (β-catenin), but there is not a linear accumulation of mutational events leading to cancer." (PMID 31293968, 2019). "Comprehensive mining of published in vitro genomics data pertaining to radiosensitivity revealed that simultaneous mutations in KRAS and SMAD4, which have not been described previously in uterine cervical cancer, are associated with cancer cell radioresistance." (PMID 30220971, 2018). "The role of autophagy in cancer progression for tumors bearing mutant KRAS is not well understood and remains unclear." (PMID 30427914, 2018). "Interestingly, Sanger sequencing of the parent cell culture just two passages later (i.e., passage 4) did not detect mutant KRAS, suggesting that normal epithelial cells rapidly out‐grow cancer cells in this culture system when both are present." (PMID 29569246, 2018).
cancer (continued). "Additionally, a study that analysed survival of KRAS and BRAF mutant metastatic cancers following complete liver resection found that there were comparable overall survival rates although fewer data for BRAF mutant cancers was available." (PMID 30598662, 2018). "The different manipulations of cell cycle to apoptosis may be attributed to the negative feedback pathways existed in the cancer cells driven by mutant KRas rather than by wild-type KRas oncogenes." (PMID 29467941, 2018). "By literature mining we identified some interesting genes (as STAT3, HIF1a, NFKB1, KRAS) that have been reported to play an important role in biological processes as inflammation, EMT, coagulation and angiogenesis, which are at the basis for cancer and cardiovascular diseases." (PMID 29703138, 2018). "Importantly, non-canonical NF-κΒ utilization by KRAS-mutant cancer cells was IKΚα driven, involved RelB activation, and was required for MPE." (PMID 29445180, 2018). "As such, PIP5K1A may not be a single vulnerability for all KRAS-mutant cancers, a point that needs further investigation, especially in vivo." (PMID 30194290, 2018). "Indeed, KRAS-mutant cancer cells displayed non-canonical endogenous NF-κΒ activity evident by enhanced nuclear localization and/or DNA-binding activity of RelB, ΙκΒβ, and ΙΚΚα, which was further inducible by exogenous IL-1β." (PMID 29445180, 2018). "Hence, this chaperone could be an attractive therapeutic target for KRAS mutant NSCLC, and several HSP90 inhibitors have been developed for the treatment of cancer." (PMID 29464099, 2018). "Moreover, we provide novel evidence that mutant KRAS is indirectly responsible for non-canonical NF-κB activation, which is IKKa and RelB based, via sensitization of cancer cells to host IL-1β." (PMID 29445180, 2018). "We detected 40 somatic mutations, including 10 mutations in genes recorded in the cancer gene list (Table EV1); primarily, we observed recurrent Notch1 (SNVs 5/10, indels 5/10) and KRas (SNVs 1/10) mutations, consistent with Rosa26‐Lmo2 + Sca1‐Cre and human LMO2+ T‐ALL pathogenesis." (PMID 29880602, 2018). "One possible reason for this is that unlike our chemical screen, the previous chemical screens were not designed specifically to identify compounds that inhibit mutant KRas-harboring/KRas-dependent, but not mt KRas-harboring/KRas-independent human cancer cell lines." (PMID 30514931, 2018). "Given the complex roles of microRNAs as “fine tuners” of gene expression, it is conceivable that the microRNA expression profile of ALK-rearranged cancers might be at least partially different from EGFR- and KRAS-driven cancers, which partly share signaling pathways." (PMID 28035073, 2017). "However, insertion of leucine between codon 60 and 61 (p.Gly60_Gln61insLeu) on KRAS has not reported any previous studies and variation databases, including ClinVar and COSMIC (catalogue of somatic mutations in cancer)." (PMID 28435405, 2017). "Mutant KRAS-driven cancers are challenging to treat due to the lack of efficient targeted therapy." (PMID 28574510, 2017). "Several studies have identified synthetic lethal interactors with mutant KRAS through the use of RNAi screens in human cancer cell lines; unfortunately, this first generation of screens yielded only new information about the biology of mutant KRAS-harboring cells, not new therapeutic targets." (PMID 27096871, 2016).
cancer (continued). "While the involvement of XPR1 in the biology of KRas-driven cancers has not been previously reported, it is plausible to hypothesize that its downstream upregulation may be involved in the regulation of cell proliferation." (PMID 27894102, 2016). "Although it has been reported that several other engineered E3 ligases could dregade oncoproteins such as HER2, C-MYC, and KRAS, none of them has been further developed as an effective recombinant protein for the treatment of cancer." (PMID 27322423, 2016). "Thus, in cancer cells ROS accumulates and inactivates GAPDH leading to an energetic crisis and cell death not seen in CRC cells not harboring KRAS and BRAF mutations." (PMID 27510264, 2016). "The BRAF mutation is known to be mutually exclusive with KRAS and/or NRAS mutations in other cancers; however, in our study, mutations in BRAF did not appear to be exclusive to either the KRAS or NRAS mutation because mutations in KRAS, NRAS, and BRAF were all found in the same patient (patient #1)." (PMID 27634910, 2016). "Taken together, the results of the SEM and phenotypic cancer assays authenticate the transition of the regular epithelial MCF10A-EV phenotype towards the malignantly transformed EMT-like MCF10A-KRasG12V phenotype, secondary to constitutive activation of the oncogenic KRas." (PMID 27894102, 2016). "Notably, our approach enabled the conversion of KRAS from a non-druggable to a potentially druggable cancer target." (PMID 26009994, 2015). "There is currently no established therapy available for KRAS mutant cancers." (PMID 25992771, 2015). "Mutations in EGFR and KRAS might be two different ways of conferring cancer phenotypes, but simultaneous mutations in both the genes might be non-optimal for cancer cell survival, and in this way, mutations in EGFR and KRAS are synthetic lethal." (PMID 26427375, 2015). "Consequently the search for KRAS targeting therapies has long been high on the agenda of cancer therapeutics, although the relative lack of success has led to KRAS being labelled as an undruggable target." (PMID 25853628, 2015). "Currently, there is not an effective means to specifically target KRAS mutant cancers." (PMID 26436951, 2015). "In addition to the recurrent and early 11p LOH event in fusion negative tumors, mutation of FGFR4, KRAS, NRAS and HRAS frequently occurred at an early time point in the cancers evolutionary history." (PMID 25768946, 2015). "Using two different primer pairs that either bound within the RET kinase domain or flanked the CCDC6-RET fusion site, we confirmed by quantitative PCR that Lc2/ad cancer cells, but not several KRAS wildtype and mutant CRC cells, harbored the CCDC6-RET fusion kinase." (PMID 26078337, 2015). "The sole silencing of oncogenic KRAS may thus not be an effective therapeutic strategy in KRAS-addicted cancers, since upstream events and feedback loops are likely to attenuate or annul the effects of the therapeutic intervention." (PMID 25992771, 2015). "A previous study has suggested that cell lines harboring the KRAS mutation such as HCT116 as well as the BRAF mutation are likely to be sensitive to CH5126766, whereas RAS-mutant cancer cells may not be sensitive to other MEK inhibitors." (PMID 25422890, 2014). "Moreover, it is already known that KRAS and HMGA2 are regulated by the let-7 family (family of miRNAs that we found to be down-regulated in PDAC in our microarray) in PDAC and other cancers." (PMID 22384141, 2012). "Moreover, expanding patient benefit across a wider spectrum of KRAS-driven cancers will be fueled by emerging classes of KRAS drugs with greater potency, broader KRAS mutant coverage, and distinct modes of action, such as by targeting the active GTP-bound (ON) state of KRAS." (PMID 42001483, 2026).